TTR (transthyretin)
Diseases named in the same sentence as TTR in open-access papers (continued):
Sharing a sentence is not in itself a finding about the gene and the disease.
AL amyloidosis (continued). "Recently, a nuclear imaging technique employing 99mTc-PYP has been described as a reliable diagnostic tool for ATTR cardiac amyloidosis, which is distinguished from AL amyloidosis with high specificity, and cardiac TTR deposition can be detected at an early asymptomatic stage." (PMID 30553273, 2018). "AL amyloidosis often necessitates immediate and aggressive chemotherapy to suppress the underlying plasma cell disorder, while the management of ATTR amyloidosis may involve TTR stabilizers, gene-silencing therapies, or organ transplantation, particularly in advanced cases." (PMID 40019577, 2025). "The imaging results showed typical transthyretin deposition, confirming the diagnosis of ATTR-CA and effectively ruling out AL amyloidosis." (PMID 40406049, 2025). "In conclusion, nuclear techniques provide multimodal and effective tools for the noninvasive diagnosis of ATTR-related CA with bone-avid tracers and the assessment of cardiac denervation in TTR and AL amyloidosis with 123I-MIBG." (PMID 41464866, 2025). "Though there are more than 30 known amyloid types affecting humans, transthyretin (ATTR) and light-chain (AL) amyloidosis are the most likely to involve the heart." (PMID 39027769, 2024). "The main subtypes of systemic amyloidosis are AL amyloidosis and ATTR amyloidosis (with amyloid deposits made up of transthyretin [TTR])." (PMID 39503010, 2024). "Forty-two amyloidogenic proteins have been identified to date, but the two most common subtypes affecting the heart, accounting for more than 95% of all cases, are transthyretin (ATTR) and light chain (AL) amyloidosis." (PMID 37367421, 2023). "Most of the CA were transthyretin (ATTR-CM, 84.6%), with a minority of cardiac light-chain amyloidosis (AL-CM, 2.2%)." (PMID 36983274, 2023). "LAS and LASR were also analyzed concerning differences between patients with transthyretin (ATTR) and light chain amyloidosis (AL)." (PMID 35683537, 2022). "While this agent is frequently cited in management guidelines for patients afflicted with either TTR or AL amyloidosis, its efficacy and safety have not been specifically investigated in individuals with CA." (PMID 41464866, 2025). "AL amyloidosis requires urgent chemotherapy targeting the plasma cell clone, while ATTR amyloidosis may be managed with transthyretin-stabilizing agents." (PMID 40427056, 2025). "More than 30 fibril-forming proteins have been found, although the mostfrequent are represented by transthyretin and misfolded monoclonal immunoglobulinlight chains, which lead to two different clinical forms called transthyretinamyloidosis (ATTR) and light-chain amyloidosis (AL)." (PMID 39077571, 2023). "The systemic amyloidosis category groups the following entities (with the involved protein in parentheses): AL amyloidosis (immunoglobulin light chain), ATTR amyloidosis (transthyretin protein both familial and senile), and ABeta2M amyloidosis (beta 2 microglobulin)." (PMID 38255657, 2023). "Systemic AL amyloidosis requires treatment targeted against the abnormal plasma cell clone, whereas therapy for ATTR CA must be targeted to the production and stabilization of the TTR molecule." (PMID 33817700, 2021). "Genetic testing of TTR revealed no mutations in positive 99mTc-PYP patients and AL amyloidosis was ruled out in all patients." (PMID 34242301, 2021). "In mouse models of AL amyloidosis, doxycycline similarly disaggregated amyloid and improved tissue markers of TTR deposition, without effecting pre-fibril aggregates." (PMID 26664897, 2015). "However, all the publications on these studies assert that these patients had TTR, but not AL amyloidosis." (PMID 31878928, 2019). "Radionuclide imaging plays a pivotal role in diagnosing transthyretin (ATTR) amyloidosis, particularly in distinguishing it from AL amyloidosis without the need for biopsy." (PMID 41517421, 2025).
heart failure (134 papers, 2013 to 2026). Inability of the heart to pump blood at an adequate rate to meet tissue metabolic requirements. "Among the 11 patients with TTR-CA included in the present study (3 with hereditary TTR-CA [genetic; hATTR] and 8 with wild-type TTR-CA [senile; wtATTR]), 1 patient died of cardiovascular cause and 6 patients experienced hospitalization for heart failure." (PMID 39841643, 2025). "Other studies suggest that lower circulating TTR levels are associated with all-cause mortality and risk of heart failure, making it a robust biomarker of systematic aging." (PMID 41278792, 2025). "Research has shown that low levels of TTR increase the risk for heart failure, as well as all-cause and cardiovascular death compared with normal TTR levels." (PMID 40717228, 2025). "Findings from several population cohort studies link low TTR levels with increasing risks of heart failure, coronary artery disease, all-cause mortality, and cardiovascular mortality." (PMID 40717228, 2025). "Recent observations in the UK Biobank showed that carriers of the TTR pathogenic variant p.V142I have reduced TTR levels, with low TTR levels associated with increased risks of heart failure, cardiovascular mortality, and all-cause mortality." (PMID 40717228, 2025). "Longitudinal analysis showed that individuals with low TTR levels were at a higher risk of heart failure and other adverse cardiovascular outcomes." (PMID 39043640, 2024). "Additional analyses were performed by treating SBP-TTr as continuous data, and by using restricted cubic spline graphs to display the relationship between TTR and all-cause death, major bleeding and heart failure." (PMID 38191585, 2024). "Transthyretin amyloid cardiomyopathy (ATTR-CM) is a complex and serious form of heart failure caused by the accumulation of transthyretin amyloid protein in the heart muscle." (PMID 38248088, 2024). "This study shows that individuals with low transthyretin levels, such as those carrying the V142I variant, are at a higher risk of heart failure and mortality." (PMID 39043640, 2024). "Carrying the V142I TTR variant has been associated with an increased risk of heart failure and mortality." (PMID 39043640, 2024). "Apart from overall survival, this study demonstrated that low TTR levels also increase the risk of additional adverse clinical outcomes such as heart failure, cardiovascular mortality, cardiovascular disease, and atherosclerotic cardiovascular disease." (PMID 39043640, 2024). "With the relatively high allele frequency of V142I and the estimated adjusted odds ratio for the risk of heart failure estimated at ~1.5–1.8 in TTR V142I carriers, many patients are either undiagnosed or at risk for being diagnosed in the future." (PMID 38541013, 2024). "Prior literature has demonstrated that individuals carrying the V142I TTR destabilizing genetic variant have an increased risk of heart failure due to deposition of misfolded TTR fibrils in the heart." (PMID 39043640, 2024). "Given the association between low transthyretin concentrations and heart failure, the heart diseases of the patients were described." (PMID 39478501, 2024). "In a heart failure study, low transthyretin was reported to be associated with older age and lower albumin and HB." (PMID 36960201, 2023). "Transthyretin related cardiac amyloidosis (TTR-CA) is an infiltrative cardiomyopathy that cause heart failure with preserved ejection fraction, mainly in aging people." (PMID 37025682, 2023). "In ATTR-CM, TTR amyloid fibrils in the myocardium cause diastolic dysfunction and eventual symptomatic heart failure." (PMID 35840997, 2022). "As an example, The TTR variant (V122I) is present in 3–4% of Black individuals and has been implicated in the pathophysiology of heart failure in the elderly, often unrecognized." (PMID 35995766, 2022). "ATTR amyloidosis causes heart failure through the accumulation of misfolded transthyretin in cardiac muscle." (PMID 34876572, 2021).
heart failure (continued). "The V122I variant of the TTR protein is being increasingly recognized as an underdiagnosed cause of heart failure in elderly African American patients, 3–4% of which appear to carry the gene." (PMID 30509186, 2018). "Several studies have showed that the lower serum TTR concentration is independently associated with higher mortality in severe clinical conditions as heart failure or both hemodialysis and peritoneal dialysis." (PMID 28636639, 2017). "Misfolded protein aggregation leading to heart failure has been found to be caused by misfolded TTR and excessive immunoglobulin resulting from aging or mutations and MM, respectively." (PMID 26664897, 2015). "A study using data from two prospective cohort studies of the Danish general population supported the association between incident heart failure and low TTR levels, suggesting that TTR levels may act as a biomarker for heart failure." (PMID 40717228, 2025). "Furthermore, lower TTR levels are associated with an increased risk of heart failure, cardiovascular disease, atherosclerotic cardiovascular disease, all-cause mortality, and cardiovascular mortality." (PMID 39043640, 2024). "The prevalence and incidence of CA is increasing due to improved diagnostics and awareness of treating cardiologists, and studies have shown that TTR-amyloid deposits are the cause of cardiac insufficiency in 13-17% of patients with heart failure with preserved ejection fraction (HFpEF)." (PMID 38809394, 2024). "Transthyretin amyloid cardiomyopathy (ATTR‐CM) is a progressive, life‐threatening disease caused by deposition of misfolded aggregated transthyretin (TTR) in the form of amyloid fibres, which accumulate within the myocardial extracellular space and give rise clinically to heart failure." (PMID 36575133, 2022). "In this study, we show a novel association in a clinically relevant polymorphism in TTR (Transthyretein), which is associated with increased risk of heart failure in Black individuals, and an unknown metabolite feature we identify as all-trans-retinol." (PMID 35995766, 2022). "Recently, low plasma transthyretin concentration has been shown to associate with incident heart failure in the general population, and it is suggested that low plasma TTR levels could be a biomarker of transthyretin tetramer instability." (PMID 35216460, 2022). "Interestingly, when people with different TTR variants were compared, TTR levels decreased and heart failure risk increased in descending order of the tetramer stability of the variant; carriers of the known stabilizing TTR variant p.T139M had the lowest disease risk." (PMID 40717228, 2025). "Importantly, V122I TTR carriers were at a higher adjusted risk of heart failure (HR 3.82, 95% CI 1.80–8.13, P < 0.001), cardiovascular death (HR 2.65, 95% CI 1.14–6.15, P = 0.023), and all-cause mortality (HR 1.95, 95% CI 1.08–3.51, P = 0.026) compared to non-carriers." (PMID 39537877, 2025). "Transthyretin amyloid cardiomyopathy (ATTR-CM) is a progressive, life-threatening disease caused by the pathological deposition of misfolded transthyretin (TTR) protein in the myocardium, leading to restrictive cardiomyopathy and heart failure." (PMID 40056371, 2025). "ATTR-CA results from the deposition of misfolded transthyretin proteins in the myocardial extracellular matrix, leading to progressive diastolic dysfunction, conduction abnormalities, and heart failure symptoms." (PMID 40951186, 2025). "A gap in current day guidelines is the role of TTR stabilizers and silencers in the management of heart failure." (PMID 41149834, 2025). "Considering the late age of phenotypic presentation in V142I carriers, serial TTR level measurement in family members who are asymptomatic V142I carriers may be a useful risk stratification tool to estimate their risk of developing heart failure and guide preventive measures." (PMID 39043640, 2024).
heart failure (continued). "Over the median follow-up of 13.7 (13.0–14.4) years, there were 401 (2.6%) and 494 (3.1%) events of heart failure in individuals with high and low TTR levels, respectively." (PMID 39043640, 2024). "The availability of TTR-targeting therapeutics has changed the outlook for patients with ATTR-CM, significantly reducing heart failure hospitalizations and all-cause mortality, while preserving exercise capacity and quality of life." (PMID 39274501, 2024). "The authors demonstrated that the ML model had good performance for detecting individuals with cCA in the derivation cohort and all four validation cohorts, giving a structured framework to raise suspicion of transthyretin CA in patients with heart failure." (PMID 36982754, 2023). "AApoAIV-CA most commonly presented with heart failure (n=12, 80%), and a lower median estimated glomerular filtration rate than AL-CA and transthyretin CA (36 mL/[min·1.73 m2] versus 65 mL/[min·1.73 m2] versus 63 mL/[min·1.73 m2], P<0.001)." (PMID 37431665, 2023). "Further studies are needed to better characterize the molecular mechanisms relating inflammation with TTR expression and/or its structural conformation in heart failure and the potential relevance of TTR monomers on the ADHF pathophysiology." (PMID 35216460, 2022). "Amyloid deposits of wild-type TTR fibrils are observed in patients with heart failure with preserved ejection fraction (HFpEF), and TTR amyloid infiltration is a pathological factor in HFpEF clinical syndrome." (PMID 34359938, 2021). "Transthyretin CA is a progressive disorder and patients ultimately develop heart failure, dysrhythmias, and cardiac conduction disturbances, which result in decreased functional capacity, diminished quality of life, and eventually death." (PMID 32969287, 2020). "IL6 stimulates angiotensinogen, serum amyloid P, fibrinogen, and orosomucoid-1 and inhibits transthyretin signifying men who developed heart failure had increased IL6 activity, whereas women with heart failure had decreased IL6 activity." (PMID 30132266, 2018). "Outcomes cannot be attributed to the pacing strategy alone, as age, comorbidities, disease-modifying treatments such as transthyretin stabilizers (e.g., tafamidis), and heart failure therapies all influence disease progression and competing risks of morbidity and mortality." (PMID 41517554, 2025). "In the Atherosclerosis Risk in Communities study, V122I TTR variant Black carriers (n = 124) were found to be at an increased risk of incident heart failure as compared to noncarriers over a 21.5 years of follow-up." (PMID 40712265, 2025). "No additional TTR gene sequence variants were found in the TTR wildtype V142V patients with heart failure or arrhythmia who had additional amyloid-related diagnoses." (PMID 38541013, 2024). "Given the relatively cardiac-specific phenotype of TTR V142I ATTR-CM, analyzing a small sample size of heart failure patients with additional amyloid diagnoses likely did not enrich for patients with TTR mutations." (PMID 38541013, 2024). "This study supports that V142I carriers have lower TTR levels compared with non-carriers and low TTR levels are associated with an increased risk of heart failure." (PMID 39043640, 2024). "Dilated or restrictive cardiomyopathies, including hypertrophic, transthyretin amyloid, and chemotherapy-induced heart failure may have different responses." (PMID 37023139, 2023). "Among family members, the proband had the lowest TTR concentration with symptoms of heart failure." (PMID 36776255, 2023). "The TTR V122I polymorphism described in 3–4% of Black individuals destabilizes the TTR-RBP4 tetramer, thereby displacing RBP4 and promoting amyloid fibril formation that precipitates heart failure and death." (PMID 35995766, 2022). "Women who went on to develop heart failure had significant upregulation of transthyretin." (PMID 30132266, 2018).
heart failure (continued). "In addition, treatment with transthyretin tetramer kinetic stabilizers was associated with an improved prognosis in patients with ATTR-CM without heart failure symptoms." (PMID 40557028, 2025). "ATTR-CM should be explored as an etiology of heart failure symptoms, and therapy should be geared towards initiation of GDMT in addition to the promising benefits of the new oral transthyretin stabilizing agents." (PMID 40134993, 2025). "In the vast majority of cases light-chain (AL) or transthyretin (ATTR) amyloid deposits are responsible for CA, leading to systolic and diastolic dysfunction, hypertrophy, arrhythmias, conduction blocks, and heart failure." (PMID 35562639, 2023). "After initiating the transthyretin stabilizer tafamidis, the patient did not experience another heart failure exacerbation." (PMID 34917152, 2021). "In addition to supportive heart failure therapy, specific treatment options are available for both ATTR (liver transplantation, novel TTR-specific treatment) and AL (chemotherapy, autologous stem cell transplantation)." (PMID 27899132, 2016). "For example, TTR‐CA patients may not tolerate standard heart failure drugs, and, if not adequately recognized, jeopardize epidemiology and results of HFpEF trials." (PMID 34390490, 2021).